FOXP3 (forkhead box P3)
Diseases named in the same sentence as FOXP3 in open-access papers (continued):
Sharing a sentence is not in itself a finding about the gene and the disease.
tumor (continued). "It has been shown that a subpopulation of the FOXP3+ T-regulatory cells, which express CXCR3, is more prevalent among the tumor associated as well as tumor infiltrating lymphocytes." (PMID 24384839, 2013). "Remarkably, tumor-induced activation of Foxp3− CD4+ T cells in drLN also resulted in their differentiation into GzmB-producing cells, suggesting a potential cytotoxic role for these cells." (PMID 22890822, 2013). "The lowest levels (0.90 ± 0.2%) of FOXP3+ Tregs were seen in the blood of patients whose tumours underwent a cPR (grade 5) following 8 cycles of NAC." (PMID 23320561, 2013). "In the presence of a TGF-ß-producing pancreatic Pan02 tumor, the transferred T-cells converted into Foxp3+ pTregs, but few FoxP3+-converted cells were found when mice were transplanted with a TGF-ß-negative esophageal Eso2 tumors." (PMID 24133490, 2013). "The expression of Foxp3 has been evidenced in a significant number of cancer types, although its role in tumor progression remains to be elucidated." (PMID 24350059, 2013). "In this light, MDSC-derived TGFβ not only suppresses cytolytic activity of T lymphocytes, but it has also been demonstrated in the B16 murine melanoma model to promote expansion of CD4+ CD25+ FOXP3+ Tregs in both tumors and tumor-draining lymph nodes." (PMID 23874338, 2013). "FOXP3, in particular, has been widely used as a single marker to evaluate the prognostic value of tumor infiltrating Treg." (PMID 23977174, 2013). "On the contrary, FoxP3+ TIL density in the tumor center stromal compartment was strongly negatively associated with T4 stage (p = 0.01), node invasion (p<0.001), VELIPI criteria (p = 0.002) and stages III-IV (p<0.001)." (PMID 23613769, 2013). "In one report, there was a positive trend toward increased presence of a sizable fraction of Foxp3+ cells which exhibited low expression levels of Nrp-1 in the tumor tissue of tumor-bearing mice." (PMID 23874336, 2013). "Curiel and colleagues reported that the presence of high numbers of CD4+FoxP3+ T cells in malignant ascites of patients with ovarian carcinomas correlated with advanced tumor staging and reduced survival." (PMID 23533029, 2013). "At last, de novo conversion of FoxP3- cells into Treg was shown to occur in the tumor as a consequence of TGF-β stimulation or IDO induction." (PMID 23763830, 2013). "It is likely that the tumor-infiltrating CD4+ T cell pool is highly heterogeneous comprising both Foxp3+ and Foxp3− suppressor cells." (PMID 23874342, 2013). "It appears that in terms of T cell-mediated immunosuppression in the tumor microenvironment, Foxp3+ Tregs are just one subpopulation of suppressor T cell." (PMID 23874342, 2013). "Studies showed that the majority of Foxp3+Tregs accumulating in the tumor microenvironment were expressing inducible costimulator (ICOS)." (PMID 24124553, 2013). "The expansion of PD1-expressing cells was closely correlated with anti-tumor immune modulation, especially when combined with increased intra-tumoral infiltration of FoxP3-positive regulatory T cells." (PMID 24349382, 2013). "The results showed that Foxp3+ cells mainly assemble in the sites close to hypoxic tumor region with high HIF-1α expression." (PMID 23723999, 2013). "In order to further explore the mechanism of SLC mediated anti-tumor effect, infiltrated CD25+Foxp3+Tregs in the tumor sites were also tested by FACS and IHC." (PMID 24078089, 2013). "Foxp3+Treg depletion can evoke effective tumor immunity and has led to tumor rejection in several animal models." (PMID 23725550, 2013). "Expression of Foxp3 by cancer cells would enable them to downregulate effector T cell responses directed against the tumor." (PMID 23382847, 2013). "In particular, the contribution of Foxp3 expression related to tumor cells as compared to the expression related to Treg in clinical CRC has not been evaluated so far." (PMID 23382847, 2013).
tumor (continued). "In a recent study conducted on 65 patients with different stages of CRC, FOXP3 expression was systematically evaluated in both tumor-infiltrating lymphocytes and neoplastic cells, and was correlated to tumor progression and clinical-pathological features." (PMID 23986759, 2013). "Taken together, these data indicate that tumor-derived VEGF is required to attract CD4+Foxp3+Nrp1+ T cells that can support tumor growth." (PMID 24324469, 2013). "Higher numbers of Foxp3+Tregs have been observed in the peripheral blood of cancer patients, in ascites, in the tumor microenvironment, and in tumor draining lymph nodes in a variety of solid cancers." (PMID 23725550, 2013). "We have previously demonstrated that targeting Tregs by vaccination of mice with murine FOXP3 mRNA-transfected dendritic cells (DCs) elicits FOXP3-specific T cell responses and enhances tumor immunity." (PMID 23341929, 2013). "In vivo, EEC inhibited tumor growth and enhanced the immune responses in mice, while the expression of PD-L1, Foxp3 and TGF-β was inhibited in the tumor tissue." (PMID 23946814, 2013). "The forkhead box protein 3 (FOXP3) transcription factor is highly expressed in tumor cells as well as in regulatory T cells (Tregs)." (PMID 24649219, 2013). "Inhibition of tumor growth was associated with reduced frequencies of Tregs and MDSC but enhanced recruitment of CCR7+Foxp3− T cells." (PMID 23874342, 2013). "Has our understanding thus far of intra-tumoral Foxp3+ T cell-enrichment identified mechanisms through which their potential influence on the anti-tumor immune response can be modulated and used to improve current T cell-orientated treatments ?" (PMID 23874342, 2013). "After 8 cycles of NAC, there was a significantly reduced % of CD4+CD25+CD127- FOXP3+Tregs, compared with pre-treatment levels, in patients who had a good pathological response in their tumours (Group I and II) (p = 0.033)." (PMID 23320561, 2013). "In this retrospective case-control study, we examined the prognostic value of FOXP3 with respect to recurrence of OSCC taking into account the subcellular localization of FOXP3 within CD4+tumor infiltrating cells." (PMID 23977174, 2013). "The non-Treg pool produced some IFN-γ and its frequency returned to normal levels after tumor removal, thus probably representing aberrantly activated Tconv, or Treg with attenuated FOXP3 activity." (PMID 23986759, 2013). "Regulatory T cells (Treg) expressing the transcription factor forkhead-box protein P3 (Foxp3) have been identified to counteract anti-tumor immune responses during tumor progression." (PMID 23382847, 2013). "The intratumoral level of Foxp3 was reversely correlated with tumor progression and we found the level of Foxp3 in the combination therapy remained the lowest among the 3 groups, which represented a beneficial anti-tumor effect." (PMID 24304581, 2013). "This was based on our previous study demonstrating that immunization with DCs transfected with FOXP3 RNA, eliminates FOXP3-expressing Tregs, and enhances tumor immunity and vaccine-induced immune responses in a murine tumor immunotherapy model." (PMID 23341929, 2013). "While CD25 mAb depletes Treg systemically, FoxP3 vaccination leads to Treg depletion intratumorally, with sparing of Treg in the periphery (outside of the tumor." (PMID 23720663, 2013). "FOXP3-expressing Tregs are reportedly abundant in the tumor infiltrates and peripheral blood of cancer patients." (PMID 24649219, 2013). "The expression of FOXP3 in T cells corresponds with immune regulatory function in the tumor microenvironment." (PMID 24040244, 2013). "FOXP3 expression in tumor cells and lymphocytes exhibited the same tendency for prognostic value based on the risk of relapse-free survival (RFS) (data not shown)." (PMID 24649219, 2013). "Of the 100 tumor specimens immunostained for FOXP3, 63 (63%) and 57 (57%) were evaluated as positive for expression in tumor cells and TILs, respectively." (PMID 24649219, 2013).
tumor (continued). "Most FOXP3 staining in tumor cells was localized to the cytoplasm [31 (31%)] or the nucleus [26 (26%)] and 6 specimens (6%) exhibited FOXP3 expression in the cytoplasm and nucleus (P=0.014)." (PMID 24649219, 2013). "In human lung adenocarcinoma, FOXP3 message amounts correlated with Th17-related transcripts enriched at the tumor site, where IL-17 antagonized the development of the anti-tumor, T-bet-dependent, Th1 response." (PMID 23986759, 2013). "A few theories have been proposed to explain how Foxp3+ T cells become enriched in tumors and in the peripheral blood of tumor-bearing hosts." (PMID 23874342, 2013). "Recent reports showed that the aggressiveness and poor outcome of T-ALL are closely related to the large number of Tregs and high expressions of Foxp3 in tumor microenvironment." (PMID 23578365, 2013). "In this study, it was found that majority of the tumor-Treg cells retain Foxp3 expression and only a minor population lost its expression providing evidence that Foxp3 expression even in an inflammatory environment as the tumor remained stable." (PMID 23874336, 2013). "Immunohistochemical analysis of FoxP3+ cells within MCA tumor tissues revealed an average 2-fold increased Treg numbers in Il27ra−/− compared to Il27ra+/+ mice." (PMID 23554861, 2013). "In man, Tregs (CD4+ CD25+ FOXP3+ (Forkhead Box Protein 3)) have been documented in blood, lymph nodes, ascites and infiltrating the tumour microenvironment in a variety of solid cancers." (PMID 23320561, 2013). "CD4+CD25+Foxp3+ cells were significantly reduced in the total splenocytes as well as tumor tissues from HS-1793 (resveratrol analog)-administered mice, and the production of TGF-β inducing Treg showed a similar pattern." (PMID 24073240, 2013). "In adoptive transfer experiments, purified CD4+CD25− T cells transferred into tumor bearing mice have been shown to convert into Foxp3+CD4+CD25+ cells within the tumor microenvironment." (PMID 23874342, 2013). "The percentage of tumor-infiltrating Foxp3+CD4+ T cells was significantly decreased in tumors treated with gemcitabine, anti-CTLA-4 or the combination treatment, a finding consistent with previously published data." (PMID 23626745, 2013). "In a study of patients with basal-like breast cancers, infiltration with Foxp3+ cells was shown, as above, to correlate with tumor hypoxia." (PMID 23874342, 2013). "Again in this case FOXP3 expression in tumor cells correlates with better relapse free and overall survival." (PMID 23861693, 2013). "A similar trend was also found between the expression of HIF-1α (P<0.001) or Foxp3 (P = 0.008) and tumor stage." (PMID 23723999, 2013). "An increase was observed in Foxp3 expression during tumor growth in a time-dependent manner by flow cytometry at 7 (1.47%), 14 (21.57%) and 21 (89.25%) days." (PMID 24179494, 2013). "Lymphocyte activation gene-3 (LAG-3), a CD4 homolog that binds MHC class II is yet another molecule that has been described to distinguish a unique sub-population of CD4+Foxp3+ Treg cells that expand at tumor sites." (PMID 23874336, 2013). "With these questions in mind, it is imperative that we continue to characterize tumor-infiltrating T cell pools with respect to deciphering the origins, specificities, and phenotypes of both Foxp3+ and Foxp3− Tregs cells and their targets." (PMID 23874342, 2013). "On the other hand, ectopic expression of Foxp3 in conventional T-cells confers immunosuppressive activities, suppressing normal T cell immunity against tumor." (PMID 23578365, 2013). "Correlation between FoxP3+ tumor-infiltrating lymphocyte (TIL) density in stromal compartment of tumor center and clinicopathological variables." (PMID 23613769, 2013). "The presence of FoxP3+CD4+CD25+ T regulatory cells (Tregs) possibly with immunosuppressive activity was evaluated in tumor tissues, inflammatory tissue and draining lymph nodes (LNs) in 198 PDAC patients and 15 patients with non-neoplastic lesions." (PMID 23950747, 2013).
tumor (continued). "We also find that, in addition to its capacity to trigger immunogenic cell death, BLM induces expansion of Foxp3+ regulatory T (Treg) cells via its capacity to induce transforming growth factor beta (TGFβ) secretion by tumor cells." (PMID 23762310, 2013). "On the other hand, IL-17 indirectly attracts Foxp3+ Tregs, enhances their suppressor function, and induces IL-9 production by Foxp3+ Tregs; in turn, IL-9 strengthens the survival and protumor effects of mast cells in the tumor microenvironment." (PMID 22615941, 2012). "We observed that FOXP3 gene up regulation in tumor infiltrating lymphocytes expanded in vitro for adopted transfer therapy is associated with likelihood of response to therapy (unpublished observation)." (PMID 22911710, 2012). "As a measurement of the relative number of cytotoxic and regulatory T-cells in the tumors, the ratio of tumor infiltrating CD8+ and Foxp3+ cells was calculated for each tumor." (PMID 22701698, 2012). "Pam3CSK4, a TLR1/TLR2 ligand can induce tumor remission in severe combined immunodeficiency (SCID) mice by diminishing the suppressive function of Foxp3+ Treg cells and enhancing the cytotoxicity of tumor-specific CTLs." (PMID 22737174, 2012). "Further, systemic depletion of Foxp3+ Tregs enhances natural as well as vaccine-induced anti-tumor T cell responses, as does targeting CD11b+ myeloid cells." (PMID 22912933, 2012). "In conclusion, tumor infiltrating CD8+ and Foxp3+ cells in TSCC display different profiles depending on tumor HPV status and clinical outcome." (PMID 22701698, 2012). "We performed an in vitro chemotaxis assay with the chemokine ligands for CCR8 and CXCR4 (CCL1 and CXCL12) and observed these chemokines induced more efficient chemotaxis of tumor-infiltrating FoxP3+ T cells compared to their counterparts in lymph nodes." (PMID 22292042, 2012). "CXCR4, while expressed by FoxP3+ T cells of both tissues, was better expressed by tumor-infiltrating FoxP3+ T cells." (PMID 22292042, 2012). "The density of FoxP3+ infiltration was similar in tumor stroma and epithelia, whereas CD8+ was higher in stroma." (PMID 22879926, 2012). "By taking advantage of a comprehensive clinical follow-up database, numbers of CD4+, FOXP3+ and IL-17+ TILs and their occurrence in different tumor compartments was correlated with clinico-pathological features and survival data." (PMID 22471961, 2012). "FoxP3+ T cells suppress the anti-tumor effector function of both CD4+ Th1 cells and cytolytic CD8+ T cells." (PMID 22292042, 2012). "Foxp3 expression was detectable in the early stages of tumor development (10 days after the intracranial injection) but disappeared with tumor progression (20 days after the intracranial injection)." (PMID 23888189, 2012). "In total, these data show that the predominant FoxP3+ population found within tumor parenchyma expresses Helios and proliferates more robustly in comparison to their Helios− counterparts." (PMID 22479644, 2012). "We observed that tumor-infiltrating FoxP3+ T cells highly expressed CCR8, while lymph node-residing FoxP3+ T cells express CCR8 at a relatively lower level." (PMID 22292042, 2012). "Our data indicate that tumor-infiltrating FoxP3+ T cells are largely positive for Helios expression." (PMID 22292042, 2012). "FoxP3+ T cells can suppress anti-tumor immunity, and depletion of these cells using anti-CD25 antibody or cyclophosphamide was effective in eradicating some transplantable tumors in animals." (PMID 22292042, 2012). "An increase of circulating and tumor-infiltrating FoxP3+ Treg cells has been reported in HCC patients." (PMID 22666283, 2012). "Human FoxP3+ Tregs have also been shown to possess an effector differentiation program resulting in the production of IL-17 that was shown to inhibit tumor growth by a T cell-dependent mechanism." (PMID 22879926, 2012).
tumor (continued). "Tregs have also been found in both the tumour mass and periphery of ovarian cancer patients and increased Tregs or even FoxP3 transcripts within the tumour mass correlate with reduced survival." (PMID 24213326, 2012). "A potential way to increase the number of tumor-infiltrating FoxP3+ T cells is through efficient conversion of FoxP3− T cells into FoxP3+ T cells in tumors." (PMID 22292042, 2012). "We, therefore, tested if immunomodulation with SA-4-1BBL affects the conversion of conventional CD4+ T cells into CD4+CD25+FoxP3+ T cells in the tumor microenvironment and peripheral lymphoid tissues." (PMID 22870329, 2012). "In other tumor types, however, the number of FoxP3+ T cells positively correlated with the patient survival rate." (PMID 22292042, 2012). "Overexpression of Foxp3 in MM cases suggests an accumulation of immunosuppressive Tregs in the tumor environment and/or an immediate involvement of this gene in the development and progression of myeloma." (PMID 22489248, 2012). "Alternatively, anti-CD4 Ab used to deplete CD4+ T cells will also eliminate CD4+CD25+Foxp3+ Treg cells, which have been shown to play a critical role in tumor-mediated tolerance of Teff cells." (PMID 23144888, 2012). "On day 18 after implantation the mice were killed and CD25+Foxp3+ levels in their excised spleens and tumor-infiltrating lymphocytes (TIL) were measured by flow cytometry." (PMID 22323550, 2012). "Patients with higher number of tumor infiltrating FOXP3+ cells at study entry seem to have better response to antibiotics." (PMID 23284739, 2012). "FoxP3+ T cells were injected into A20 tumor-bearing mice and their migration into tumors within the 36 h time period was examined." (PMID 22292042, 2012). "Flow cytometric analyses of CD45.2+ TILs revealed a decrease in the percentage of CD4+CD25+Foxp3+ Tregs in tumor infiltrates from vaccinated mice versus controls." (PMID 22860107, 2012). "There was a pronounced reduction in the percentage and absolute number of OT-II CD4+FoxP3.gfp+ T cells harvested from the spleen, tumor-draining lymph nodes, and tumor of mice treated with SA-4-1BBL as compared with untreated controls." (PMID 22870329, 2012). "In conclusion, CCL17 and CCL22 within the tumor are related to the increased population of Foxp3+ Tregs, with such an observation occurring in early GC." (PMID 22693525, 2012). "The anti-tumor efficacy of the ESC/STO-GM vaccine also correlated with significantly higher intra-tumoral CD8+ T/CD4+CD25+Foxp3+ Tregs ratio." (PMID 22860107, 2012). "Number of Foxp3+ and CD8+ T-cells and CD8+/Foxp3+ cell ratio by clinical outcome and tumor HPV status." (PMID 22701698, 2012). "Whiteside’s group reported that tumor-derived microvesicles induce the expansion of CD4+ CD25+ FoxP3+ cells while inducing apoptosis of tumor-reactive CD8+ T cells." (PMID 22738135, 2012). "We also co-transferred CCR7 (+/+) and CCR7 (−/−) FoxP3+ T cells for competitive population in tumor-bearing scurfy mice." (PMID 22292042, 2012). "We observed that tumor-infiltrating FoxP3+ T cells highly express CCR8 and CXCR4, chemokine receptors associated respectively with memory cells and tumors." (PMID 22292042, 2012). "There was an almost complete demethylation of the FOXP3 promoter in the CD4+FOXP3+ cells from both the tumor and unaffected tissue, indicating that they stably express FOXP3." (PMID 22319577, 2012). "Kinetics of both infiltrating FOXP3+ cells and tumor CD20+ cells were strongly dependent on the treatment administered." (PMID 23284739, 2012). "In murine models, selective elimination of Treg cells (i.e., CD4 + CD25 + FOXP3+) restores an effective anti-tumor immune response leading to tumor regression." (PMID 22383042, 2012). "Kinetics of both infiltrating FOXP3+ cells and tumor CD20+ cells were strongly dependent on the treatment administered, showing different patterns between cases treated with antibiotics and those treated with immunochemotherapy." (PMID 23284739, 2012).